STAT3 (signal transducer and activator of transcription 3)
Diseases named in the same sentence as STAT3 in open-access papers (continued):
Sharing a sentence is not in itself a finding about the gene and the disease.
cancer (continued). "In colorectal cancer tissues, B7-H3 induces cancer cell migration and invasion through the Jak2/Stat3/MMP-9 signaling pathway." (PMID 40519928, 2025). "Among the STAT family members, STAT3 is the most frequently activated in cancer and contributes to malignant transformation and progression." (PMID 40867898, 2025). "Another critical unmet need is the lack of reliable biomarkers for early detection and monitoring of STAT3 activation in cancer cachexia." (PMID 40704145, 2025). "While STAT3 signaling has been thoroughly examined in cancer and fibrotic diseases, its involvement in lens epithelial cells and EMT remains predominantly unexplored." (PMID 40641526, 2025). "Personalized treatment paradigms are likely to represent the future direction of STAT3-based therapies in cancer cachexia." (PMID 40704145, 2025). "Within the TME, IL-6 signaling activates STAT3 in cancer cells, driving EMT and recruiting immunosuppressive myeloid populations that facilitate metastasis." (PMID 41394398, 2025). "In these cells, UA induces apoptosis, arrests the cell cycle, and inhibits cancer cell proliferation by downregulating key proteins such as STAT3, EGFR, and cyclin D1." (PMID 40141751, 2025). "Signal transducer and activator of transcription 3 (STAT3) is widely recognized as an attractive target for cancer therapy due to its significant role in the initiation and progression of tumorigenesis." (PMID 40118821, 2025). "Component in numerous cancers and cell lines, STAT3 activation plays a crucial part in the formation and carcinogenesis of malignancies." (PMID 40350446, 2025). "Its molecular targets include NF-κB and AP-1 (activator protein 1), STAT3 (signal transducer and activator of transcription 3), and other carcinogenesis-related signaling proteins involved in the occurrence and development of cancer." (PMID 40733206, 2025). "A deeper understanding of the upstream regulatory mechanisms of STAT3 is important for discovering novel targets for cancer treatment." (PMID 41281755, 2025). "The complex interplay between noncoding RNAs and the STAT3 pathway contributes to cancer cell proliferation, metastasis, and therapeutic resistance in gastric and other gastrointestinal cancers." (PMID 40860906, 2025). "In adult cancers, acquired oncogenic alterations and age-related immune decline contribute to altered expression of NF-κB, IL-6 (a downstream target of NF-κB), and STAT3 signaling, altering immune recognition and cellular senescence." (PMID 39796780, 2025). "Normally, STAT3 activation is transient and tightly regulated in healthy cells; however, in many cancers, STAT3 is constitutively active thus promoting cell proliferation, invasion, drug resistance, and immune cell evasion." (PMID 40075607, 2025). "Among them, the JAK/STAT3 signaling pathway led to increased tumorigenic and metastatic abilities, as well as chemoresistance in cancer, through its enhancement of the EMT." (PMID 40830747, 2025). "IL-6 can activate the STAT3 pathway in cancer cells, upregulating anti-apoptotic and drug-efflux proteins, contributing to chemotherapy resistance." (PMID 40404908, 2025). "Once activated, STAT3 translocated to the nucleus, binds to DNA, and regulates the expression of genes involved in cancer progression." (PMID 41425711, 2025). "The JAK/STAT3 pathway is critical to cancer cell survival, proliferation, immune evasion, and treatment resistance." (PMID 40350446, 2025). "Thymoquinone (TQ) has exhibited the ability to inhibit the proliferative activity of different cancer cells through ROS‐driven inhibition of the STAT3 pathway, thereby inducing apoptosis in cancer cells." (PMID 40377005, 2025).
cancer (continued). "Antibody–drug conjugates allow for more the specific targeting of cancer cells through an antibody targeting a cancer cell-specific antigen in order to deliver the drug needed to kill the cancer cells, such as a STAT3 inhibitor." (PMID 40075607, 2025). "In these studies, it has been shown that metformin induces apoptosis through critical molecules in cancers such as STAT3, as well as its direct activity on programmed cell pathways." (PMID 40091035, 2025). "The intricate interplay between NF-κB and STAT family signaling, especially STAT3, reflects their shared functions in inflammation and cancer." (PMID 40420174, 2025). "A variant of the surface marker found on the hepatitis B virus, W4P, promotes the progression of cancer via the STAT3 pathway." (PMID 39926108, 2025). "Our study uncovers a novel mechanism of STAT3 dysregulation in cancer and provides a strong basis for therapeutic targeting of the noncanonical function of a housekeeping protein." (PMID 41380973, 2025). "Mechanistically, myMAFs are driven by macrophage-derived progranulin and leukemia inhibitory factor secreted by cancer cells and are induced through a STAT3-dependent mechanism in an interactive manner." (PMID 40612677, 2025). "Current applications of STAT3 inhibitors in cancer therapy indicate that small-molecule inhibitors often have several drawbacks, including poor selectivity and specificity, inadequate cellular permeability, low bioavailability, and off-target effects." (PMID 40969747, 2025). "Activated JAK phosphorylates non-receptor tyrosine kinases essential for signaling in response to cytokines and sequentially phosphorylates STAT3; this mechanism leads to poor chemotherapeutic response in several cancers." (PMID 40696387, 2025). "The continuous activation of STAT3 in different cancers supports tumor growth, progression, and proliferation by regulating multiple signaling pathways, including Akt." (PMID 40427612, 2025). "IL-6 promotes BC via activation of proto-oncogenic STAT3 and also regulates invasive properties of BC cells, presumably by activating pro-survival and invasive gene expression program controlled by STAT3 in a context of various cancer." (PMID 40361239, 2025). "In breast cancer, the JAK2/STAT3 axis is involved in the B7-H3-mediated reduction in cancer cell sensitivity to Paclitaxel." (PMID 40214484, 2025). "Chronic inflammation not only serves as a major trigger for DNA damage but also activates multiple signaling pathways, such as NF-κB and STAT3, which induce the expression of cancer-related genes." (PMID 40421042, 2025). "STAT3 signaling, which is frequently activated in malignant tumors, correlates strongly with several malignancy traits." (PMID 40265014, 2025). "Collectively, these findings highlight pentacyclic triterpenoids as effective modulators of the JAK/STAT3 signaling pathway with promising therapeutic potential especially in cancer." (PMID 41373772, 2025). "Increased IL-6/STAT3 activation can promote cancer-cell survival and reduce the sensitivity to gemcitabine." (PMID 41425711, 2025). "Further investigation into the complex roles of STAT3 in different cancer types is essential for the development of successful therapies targeting the STAT3 signaling pathway." (PMID 40166646, 2025). "Our findings revealed that OB EVs induced significant phosphorylation of STAT3, a key signaling molecule in cancer progression, and promoted increased cell migration, dependent on fatty acid oxidation (FAO)." (PMID 40485730, 2025). "We then explore STAT3's involvement in multiple diseases, with a strong focus on cancer development and progression." (PMID 40166646, 2025). "Beta-Caryophyllene upstream effect on the JAK1/STAT3-signaling pathway was reported in several cancer studies." (PMID 40333803, 2025). "STAT3 plays a crucial role in advanced cancers by promoting glycolysis through the transcriptional activation of HIF-1α and HK2 in vitro." (PMID 39859445, 2025).
cancer (continued). "Addressing these challenges will be key to unlocking the full therapeutic potential of STAT3 modulation in managing cancer cachexia." (PMID 40704145, 2025). "STAT3 is an important transcription factor involved in the regulation of a variety of biological processes, and abnormally activated in diversified cancers." (PMID 41208976, 2025). "STAT3 not only drives oncogenic signaling but also contributes to chemoresistance, a major obstacle in cancer therapy." (PMID 40075607, 2025). "In order to clarify the molecular process that occurs when DZN and PNR together inhibit the migration and invasion of cancer cells, we looked into STAT3/FAK signaling as a possible target for medication." (PMID 40217305, 2025). "Here, we demonstrated that STAT3 expression and activation are markedly elevated in pro-tumoral TANs in cancer patients." (PMID 40885734, 2025). "STAT3 is a key transcription factor that significantly contributes to cancer development and progression by mediating cellular responses to cytokines and growth factors." (PMID 40918170, 2025). "AKT, ERK and STAT3 signaling also play essential roles in regulating the proliferation and survival of cancer cells." (PMID 40563476, 2025). "The STAT3 dimer translocates to the nucleus, binds to specific DNA sequences, and activates transcription of a broad number of genes, including cancer promoting genes." (PMID 40426911, 2025). "The activation of STAT3 has been identified as a key mechanism for conferring survival advantage on cancer cells in response to the toxic effects of chemotherapeutics, such as Cisplatin and tyrosine kinase inhibitors." (PMID 39997178, 2025). "Transcription factors play a critical role in regulating VEGFA expression, with STAT3 recognized for its ability to activate VEGFA in cancer cells." (PMID 40474298, 2025). "Current research indicates that the JAK2/STAT3 pathway plays a crucial role in promoting cancer cell growth, invasion, metastasis, and anti-apoptosis, particularly in triple-negative breast cancer, melanoma, and other tumor diseases." (PMID 39940837, 2025). "Recent therapeutic strategies have increasingly focused on targeting the STAT3 pathway to mitigate the muscle and adipose tissue wasting characteristic of cancer cachexia." (PMID 40704145, 2025). "DSCs emit IL‐6, which triggers the Stat3 and NF‐KB pathways and promotes the development of cancer cells." (PMID 41179371, 2025). "Previous studies have also found that decreased LIF expression, driven by miR‐637 overexpression, inhibits STAT3 phosphorylation and cancer cell growth in HCC." (PMID 40416597, 2025). "Taken together, these studies exposed a targetable vulnerability for cancer cells with high genomic instability, with STAT3/FA-BRCA pathway being a central component of this signaling cascade." (PMID 40038300, 2025). "In TNBC, targeting DCLK1 eliminates the malignant phenotype of cancer cells, enhances chemotherapy efficacy, and stimulates antitumor immunity by inhibiting the IL-6/STAT3 pathway." (PMID 40890855, 2025). "IL-19 plays a critical role in tumorigenesis, triggering cell proliferation and mainly activating STAT3 in several cancer cells." (PMID 40806452, 2025). "Prominosomes-primed M2-like tumor-associated macrophages showed increased secretion of cytokines and chemokines, notably interleukin-6, compared to untreated cells leading to the activation of the STAT3 pathway in EV-donor cancer cells." (PMID 39881297, 2025). "This dichotomy suggests STAT3’s physiological role in normal tissue homeostasis versus its cancer-specific hyperactivation through post-transcriptional mechanisms." (PMID 40636126, 2025).
cancer (continued). "By blocking STAT3 phosphorylation, curcumin prevents its nuclear translocation and DNA binding, thus impairing its role in driving gene transcription related to cancer cell survival and proliferation." (PMID 41020838, 2025). "Numerous studies strongly supports blocking STAT3 activation using inhibitors or knockout systems as an attractive therapeutic target for cancer and other human diseases." (PMID 40143965, 2025). "Ki67 and cleaved-caspase 3 immunohistochemical staining indicated increased apoptosis and decreased proliferation of cancer cells following cisplatin treatment upon blockade of the CXCL14/CCR7/STAT3/ERCC4 axis." (PMID 40898244, 2025). "Directly targeting STAT3 protein enables more specific anti-cancer activity while minimizing off-target reactions." (PMID 40118821, 2025). "The dampening of JAK/STAT3 responses in T cell subsets corroborate the proteomic results indicating that the young plasma protein fraction regulated pathways related to cancer." (PMID 39953524, 2025). "STAT3 interacts with NFκB1 at multiple levels; it extends NFκB1–nuclear retention, and together, they control the ability of cancer cells to resist apoptosis." (PMID 40149331, 2025). "In turn, KCs with LMD elicited cancer stem cell formation from HBV+ hepatocytes via Stat3 pathway, activated by the chemokine network within the crosstalk." (PMID 41164971, 2025). "In the context of cancer, the JAK2/STAT3 signaling pathway is implicated in cell proliferation and survival." (PMID 40394236, 2025). "To investigate potential factors contributing to increased cancer invasiveness, we assessed phosphorylated STAT3 and N‐cadherin levels." (PMID 39996379, 2025). "M1-like TAMs further enhance EMT and cancer stem cells (CSCs) characteristics through activating the Jak/STAT3 pathway." (PMID 40486875, 2025). "IL-6/STAT3 activation enhances resistance to apoptosis and promotes cancer cell proliferation, invasion, and metastasis." (PMID 41458591, 2025). "In nasopharyngeal cancer, sulforaphane upregulates miR-124-3p, which directly targets STAT3 signaling and reduces cancer stem cell markers, including β-catenin, Nanog, and Oct3/4 in HONE1, SUN1, CNE1, and CNE2 cell lines." (PMID 40808836, 2025). "Both studied lncRNAs have been proposed as regulators of cancer-dependent inflammatory responses, targeting the STAT3 and NF-κB pathways and promoting the production of pro-inflammatory cytokines such as TNF-α." (PMID 40150019, 2025). "JAK1, STAT1, and STAT3 expressions were stronger in PROC than in the platinum-sensitive group of primary chemotherapy-naive cancer tissues." (PMID 40883550, 2025). "RT-qPCR analysis confirmed that KDM1A and STAT3 expression levels were substantially higher in cancer cells (HSC3 and CAL27) than in normal epithelial cells." (PMID 40246812, 2025). "Recent studies have shown that most members of the USP family are involved in regulating the aberrant activation of the JAK2/STAT3 signaling pathway in malignant tumors." (PMID 40936898, 2025). "STAT3 is often overactivated in cancer, contributing to the malignant phenotype by promoting cell survival, angiogenesis, invasion, and immune evasion." (PMID 39997178, 2025). "While these natural compounds show encouraging preclinical efficacy in targeting STAT3 to alleviate cancer cachexia, further clinical studies are necessary to confirm their therapeutic potential and safety for use in treating this condition." (PMID 40704145, 2025). "C/EBPβ and STAT3 expression negatively correlates with CCL5 across multiple human tissues, while elevated C/EBPβ/STAT3 expression is associated with reduced CD8+ T cell infiltration and poor survival across various cancer types." (PMID 40749055, 2025). "STAT3 overactivation is a key event in the formation of most human cancers and plays a crucial role in cell proliferation, angiogenesis, metastasis, and immune suppression." (PMID 40128669, 2025).
cancer (continued). "This review provides a comprehensive evaluation of STAT3's role in health and disease, emphasizing its involvement in cancer stem cell maintenance, metastasis, inflammation, and drug resistance." (PMID 40166646, 2025). "B7‐H3 and c‐Met interaction is revealed to be crucial in maintaining cancer cell stemness primarily via c‐Met/STAT3 signaling pathway." (PMID 40859957, 2025). "The combination of STAT3 inhibitors with other therapeutic agents enhances both the safety and efficacy of cancer treatment while improving the therapeutic potential of STAT3 blockade through advanced drug delivery modalities." (PMID 40166646, 2025). "It has been reported that STAT3 can interact with long non-coding RNAs (lncRNAs) to regulate the occurrence and development of cancer." (PMID 41208976, 2025). "Recent evidence underscores the pivotal role of STAT family proteins, particularly STAT3, in selectively inducing and maintaining a pro-carcinogenic inflammatory microenvironment during malignant transformation and cancer progression." (PMID 40444012, 2025). "NF-κB and STAT3 interactions are vital in mediating communication between cancer and inflammatory cells." (PMID 40612951, 2025). "Both cytokines activate STAT3 signaling, which in turn induces the transcription of multiple MMPs and facilitates cancer cell invasion." (PMID 41154660, 2025). "In cancer and inflammatory cells, STAT3 activation is frequently driven by cytokines produced as a result of NF-κB signaling in the TME." (PMID 40420174, 2025). "Given the diverse functions of STAT3, the development of novel small molecules capable of directly targeting STAT3 presents a promising approach for cancer therapy." (PMID 40166646, 2025). "Hyperactivation of the STAT3 pathway contributes to key cancer hallmarks, including epithelial-to-mesenchymal transition (EMT), angiogenesis, and metastasis." (PMID 40426911, 2025). "In our recent study, we also proposed that cancer patients with low STAT3/PRAKK1 or STAT3/PRAKK2 ratio tend to have better response to Bortezomib treatment compared with those with high ratio." (PMID 41281743, 2025). "In summary, STAT3 plays a pivotal role in cancer development, progression, and acquired drug resistance, making it an attractive therapeutic target." (PMID 40860906, 2025). "Cucumber-derived nanovesicles (CDNVs) have also shown promise in cancer therapy by suppressing STAT3 activation." (PMID 40575656, 2025). "Persistent phosphorylation of STAT3 is observed in approximately 70% of human cancers, including GBM4." (PMID 41145734, 2025). "HHT reduces the expression of anti-apoptotic genes regulated by STAT3, such as Bcl-2 and Mcl-1, thereby affecting cell growth and survival in cancer cells." (PMID 39949739, 2025). "For example, IL6 secreted by CAFs activates the STAT3 signaling pathway in cancer cells and macrophages, enhancing pro-inflammatory properties and suppressing anti-tumor immune responses." (PMID 41050676, 2025). "Next, we investigated the protein expression levels of the IL-6R/phosphorylated STAT3 (p-STAT3)/HLF/TFEB/PD-L1 axis in tissues from patients with cancer." (PMID 40779629, 2025). "The compounds work through two mechanisms: they block STAT3, which controls cancer cell survival and proliferation, or bind to tubulin to disrupt microtubule formation and trigger apoptosis." (PMID 41154590, 2025). "In CRC, STAT3 is often constitutively activated, which contributes to the uncontrolled growth and survival of cancer cells." (PMID 40244518, 2025). "STAT3 is widely recognized for its role in promoting cancer progression and poor prognosis by regulating genes governing tumor survival, growth, invasion, angiogenesis, and drug resistance." (PMID 40969747, 2025). "TTI-101 targets the pY-peptide binding pocket within the Src-homology (SH) 2 domain of STAT3 and was shown to target STAT3 in mouse models for inflammation, fibrosis, and cancer." (PMID 41226842, 2025).